MTOR (mechanistic target of rapamycin kinase)
Diseases named in the same sentence as MTOR in open-access papers (continued):
Sharing a sentence is not in itself a finding about the gene and the disease.
cancer (continued). "Deregulation of the mTOR signalling pathway is implicated in multiple age-related diseases such as cancer, neurodegeneration, and auto-immunity." (PMID 32899412, 2020). "It has been confirmed that PI3K/mTOR signaling when altered/mutated, helps the normal cell to evade apoptosis and form cancer cell and helps in the generation of self-sustaining growth mechanism which leads to the development of tumors as well as cancer." (PMID 32351329, 2020). "PTEN loss resulted in the downstream activation of AKT/mTOR signaling in secondary cancer lesions and determined the overall ccRCC patient’s survival." (PMID 32668608, 2020). "The corroboration of the preclinical and clinical studies have implicated that AKT/mTOR inhibitors are emerging therapeutics for the treatment of various cancers." (PMID 32384682, 2020). "mTOR is dysregulated in various cancers due to its direct mutation, mutations of mTOR components and mutation of upstream genes including oncogenes and tumor suppressor genes." (PMID 32517736, 2020). "Because many cancer-associated recurrent mutations are clustered around the regions of mTOR that undergo some form of conformational change upon Rheb activation, it suggests that these changes are of pivotal importance for mTORC1 activity." (PMID 32759652, 2020). "Publications with different conclusions on the effect of mTOR polymorphisms on cancer risk were retrieved." (PMID 32597485, 2020). "The resistance to mTOR inhibitors is accompanied by the hyperexpression of various cancer-associated signaling proteins, among them PI3K, Akt." (PMID 32825760, 2020). "PTEN loss results in the downstream activation of AKT/mTOR signaling in secondary cancer lesions and determines the overall ccRCC patient’s survival." (PMID 32668608, 2020). "The PI3K/AKT/mTOR pathway has been implicated in the development of various types of cancer regulated by m6A proteins, including METTL3/WTAP in AML, METTL3 in RCC/PDAC, ALKBH5 in EOC, and FTO in melanoma and EC." (PMID 32513173, 2020). "Mutations in these pathways, in mTOR itself and in the mTOR complexes mTORC1 and mTORC2, account for up to 30% of all human cancers." (PMID 32012988, 2020). "Glycolysis addiction in cancer cells with high levels of Myc has been described and linked to mTOR pathway activation." (PMID 32346009, 2020). "The studies performed using established cancer cell lines were very promising; statins inhibited i.a. the mTOR signaling pathway strictly associated with cancer progression, and pro-inflammatory cytokine activity." (PMID 33255609, 2020). "It has been demonstrated that the Akt/mTOR signaling network is constitutively activated and associated with the development of several types of cancers including AML." (PMID 32850379, 2020). "Loss of PTEN leads to upregulation of mTOR signaling, and mTOR inhibitors have been used to treat multiple cancer types." (PMID 32325871, 2020). "Rapamycin which is a mTOR inhibitor, inhibits tumor growth, angiogenesis, metastasis and causes apoptosis in cancer cell lines as well as in tumor mouse models." (PMID 33258012, 2020). "The loss of PTEN leads to changes in the PI3K/AKT/mTOR pathway that affect cell energy metabolism, and the metabolic reprogramming of cancer cells is another important feature of cancer." (PMID 32875727, 2020). "Gene Set Enrichment Analysis results suggested that the expression of CHRNB4 was associated with cancer-related pathways, such as the mTOR pathway." (PMID 33304845, 2020).
cancer (continued). "The PI3K/AKT/mTOR pathway regulates the translation of mRNAs that encode pro‐oncogenic proteins, leading to malignant cell survival in various cancers." (PMID 33090698, 2020). "Increased activation of mTORC1/2 pathways due to MTOR mutations has been reported in a range of cancers." (PMID 32495998, 2020). "This relieves mTOR mRNA suppression by RNH1 and promotes cell-proliferation associated mTOR signalling and thus cancer progression." (PMID 33182489, 2020). "As already mentioned, a constitutive activation and deregulation of the PI3K/AKT/mTOR pathway is almost a hallmark of cancers cells." (PMID 32033478, 2020). "Our study links mTOR-induced cancer drug resistance to autophagy defects as a cause of a metabolic liability and opens a therapeutic window for the treatment of otherwise therapy-refractory tumor patients." (PMID 32943635, 2020). "The increased activity of the phosphoinositide 3-kinase (PI3K)/mammalian target of rapamycin (mTOR) signalling pathway has been associated with increased growth, survival, and proliferation in many human cancers." (PMID 33381351, 2020). "Cancer development and progression is often associated with constitutive activation of the mTOR pathway, thus justifying mTOR inhibition as a promising approach to cancer treatment and prevention." (PMID 32341756, 2020). "There is still no conclusion on the potential effect of the rs2295080 and rs2536 polymorphisms of mTOR (mammalian target of rapamycin) gene on different cancers." (PMID 32597485, 2020). "On the other hand, the association between Gαh activity/expression and Akt/mTOR pathway, as well as autophagosome degradation, has been demonstrated in several types of cancer cells." (PMID 32615541, 2020). "The aberrant Akt/mTOR signaling has been demonstrated to be associated with the tumorigenesis of miscellaneous cancers including AML." (PMID 32850379, 2020). "Deregulated mTOR signaling has therefore been associated with human diseases as well as with the development of cancer." (PMID 33362215, 2020). "Other mTOR associated diseases, such as cancer, have also proved to be opportunistic for GPCR drug targets, as over 20 agents were in clinical trials at the time of that publication." (PMID 32854217, 2020). "As a parallel pathway to MAPKs, and an upstream signaling pathway of NF-κB, the PI3K/Akt/mTOR signaling pathway is also linked with the regulation of inflammation and cancer cells survival." (PMID 32823876, 2020). "In a previous study, a combination of autophagy-associated mTOR inhibition and radiation yielded enhanced therapeutic effects in cancer cells and xenografted tumors." (PMID 33243298, 2020). "HSF1 has been previously linked to CAC, as its activation in cancer cells was shown to activate mTOR and increase glutaminolysis, thus promoting tumor growth." (PMID 33288768, 2020). "The Akt/mTOR signaling pathway is typically abnormally activated in a variety of malignant tumors and causes abnormal expression of downstream genes such as PFKFB2, p21, Vimentin, and Bcl-2." (PMID 33282634, 2020). "Hyperactivated mTOR complex has been implicated in many cancers, mostly as a consequence of the inhibition of the upstream regulator protein tuberous sclerosis complex (TSC)." (PMID 33228205, 2020). "Mammalian Target of Rapamycin (mTOR) is a hallmark signaling pathway in cancer including GBM, frequently taken into account as therapeutic targets in major clinical studies." (PMID 33371210, 2020). "Taken together, our findings summarize currently published evidence comprehensive investigations regarding the genetic relationship between mTOR rs2295080/rs2536 polymorphisms and the risk of different cancers." (PMID 32597485, 2020).
cancer (continued). "The depicted associations between oncogenic EVI1 and abnormally enhanced mTOR activity raise the possibility that EVI1 influences cancer prognosis and therapeutic response in a clinical setting where this kinase plays a central role, that of ccRCC." (PMID 32012804, 2020). "Previous studies have indicated that MEK or Akt inhibitor resistance in cancer can be caused by crosstalk between the PI3K/Akt/mTOR or RAF/MEK/ERK pathways." (PMID 31527768, 2019). "Deregulation of the mTOR signaling pathway is associated with a number of human diseases, including cancer, type 2 diabetes, obesity, and neurodegeneration." (PMID 30857853, 2019). "Taken together, our findings suggest that the anti-cancer effect of fisetin on HNCCs is associated with SESN2/mTOR/Mcl-1 signaling axis." (PMID 30936621, 2019). "It controls several cancer-associated genes, such as mammalian target of rapamycin (mTOR), hepatocyte growth factor receptor c-Met, the kinase p21-activated kinase 4 (PAK4), and the Notch regulator Yes-associated protein 1 (YAP1)." (PMID 31805631, 2019). "About 11, 26, and 10.5% of diffuse-type C-I, C-II, and intestinal-type GCs exhibited PIK3CA mutations in TCGA cohort, and the overall responsive rate was reported 35% for cancer patients with PIK3CA mutations treated with PI3K/AKT/mTOR pathway inhibitors." (PMID 30866995, 2019). "The phosphatidylinositol 3-kinase (PI3K)/mammalian target of rapamycin (mTOR) signaling pathway has been implicated as a cancer target." (PMID 31752127, 2019). "It has been proved that M. charantia and its extracts can modulate AKT/mTOR/p70S6K signaling, cell cycle regulatory proteins and apoptosis-associated proteins in different cancers." (PMID 30984004, 2019). "This pathway is the target of anticancer therapies; being the deregulation of mTOR activity, it is associated with numerous types of cancer." (PMID 31766386, 2019). "Activation of mTOR signaling has been associated with cancer pathogenesis, prompting investigation of rapamycin and rapalogs for the treatment of cancers." (PMID 30636722, 2019). "The mechanism of NVP-BEZ235 action against cancer cell proliferation was found to be associated with dual inhibition of PI3K/mTOR." (PMID 31370278, 2019). "As a signaling effector located downstream of PI3K, mTOR is also intimately associated with cancer initiation and development." (PMID 31069214, 2019). "This suggested possible explanations to the tumorigenic effect of GOLPH3, because deregulation of mTOR signaling is associated to tumor progression and cancer." (PMID 30779783, 2019). "For instance, miRNAs can inhibit cancer development by targeting mTORC1 or affecting other genes associated with the mTOR signalling pathway involved in proliferation, invasion, apoptosis and the cell cycle." (PMID 31371743, 2019). "Proteins of the mammalian target of rapamycin (mTOR) signaling axis are overexpressed or mutated in cancers." (PMID 30642006, 2019). "Some mTOR inhibitor-naïve tumours have been reported to contain mTOR mutations, but mTOR has also been reported to become mutated in cancers treated with mTOR inhibitors." (PMID 35582282, 2019). "It is important to underline that mTOR signaling is frequently activated in cancer cells and its activation is involved in the control of cancer cell metabolism, altering the expression/activity of many key metabolic enzymes." (PMID 30813354, 2019). "Resistance to mTOR inhibition in cancer has been linked to activation of upstream PI3K/AKT and MAPK/ERK signaling, following rapalog treatment." (PMID 31388935, 2019). "There are still challenges in cancer therapy including the activation of other proliferation signaling pathways, treatment-resistant mutations as well as the intramural heterogeneity of mTOR activities." (PMID 31075885, 2019). "Studies also found mutations in mTOR itself in various cancer types with FAT and FATC domains frequently mutated." (PMID 30754640, 2019).
cancer (continued). "The Akt/mTOR signaling pathway has been implicated in cancer development, and is frequently aberrant activated in cancers." (PMID 31889892, 2019). "Collectively, the findings of this study underline the significance of PI3K/AKT/mTOR signaling for the virus-host cell cross talk in HPV-positive cancer cells." (PMID 30755508, 2019). "We found more enriched terms linked to cancer, such as “mTOR signaling pathway”, “Jak-STAT signaling pathway”, “hematopoietic stem cell differentiation” and “response to interleukin-15” (hematopoietic growth factor." (PMID 31142264, 2019). "Metformin treatment inhibits the mTOR pathway via the inhibition of Rag GTPases in cancer cells, which in turn reduces protein synthesis and causes cell cycle arrest." (PMID 31835318, 2019). "The PI3K/Akt/mTOR pathway is associated with a variety of diseases, including cancer, obesity, and neurodegeneration." (PMID 31340526, 2019). "The important roles of mTOR signaling delve into cell migration, inflammation, and regulation of transcription factors associated with cancer progression." (PMID 31030467, 2019). "Overall, genetic amplifications and overexpression of key proteins responsible for driving mTOR activation underlie the tumour progression that is often observed in cancers, including HNSCC." (PMID 30970654, 2019). "Dysregulation of the phosphoinositide 3-kinase (PI3K)/AKT/mechanistic target of rapamycin (mTOR) axis has been implicated in most human cancer types and shown to contribute to tumorigenesis, tumor progression, and resistance to therapy." (PMID 31262325, 2019). "Being an anchor point of cell growth, mTOR signaling is a critical target of genetic variation in cancer, and when affected it is frequently associated with carcinogenesis and tumor progression." (PMID 30764584, 2019). "Hyperglycaemia is a common problem in patients with cancer, as a side-effect of numerous cancer therapies (including glucocorticoids and MTOR inhibitors) and since there is an increased risk of cancer in patients with diabetes." (PMID 30737563, 2019). "Inhibitors of mTOR are used in anti-cancer therapies and as immunosuppressants, and mTOR has been associated with the regulation of multiple elements of the cell cycle signaling including cyclins and p21." (PMID 31466420, 2019). "Extensive research has linked mTOR to several human diseases including cancer, neurodegenerative disorders, and aging." (PMID 31649622, 2019). "Salvianolic acids mechanistically proceed through modulation of various signaling networks such as MAPK, P13K/Akt, NF-κB and mTOR and pathways which are often deregulated in cancers and are also associated with drug resistance." (PMID 31592132, 2019). "On the other hand, abnormality in the mTOR-regulated pathways is associated with numerous pathological conditions including metabolic diseases, cancer, immune disorders, and cardiovascular and neurological diseases." (PMID 34691993, 2019). "Based on statistics from the Cancer Genome Atlas Pan-Cancer effort, the mTOR signaling pathway was found to be one of the highest mutated genes in 12 cancers analyzed from 3281 tumors." (PMID 31075885, 2019). "In summary treatment of tumour cells with pan-Akt and pan-mTOR synergistically inhibited the growth of cancer cells and was associated with arrest in G0/G1." (PMID 30056610, 2019). "mTOR inhibition was shown to result in Treg expansion and increased levels of Tregs have been associated with poor survival in cancer patients, including mRCC." (PMID 30413837, 2019). "The central role of mTOR in regulating cellular protein synthesis and cell survival explains the association of an overactive mTOR pathway cancer." (PMID 31835318, 2019).
cancer (continued). "The PI3K/Akt/mTOR pathway is a crucial signaling cascade that is activated in various cancers, and this pathway is associated with cell proliferation, invasion, and migration." (PMID 31091245, 2019). "As expected, in the pooled set analysis pAKT pathway activation was significantly associated will luminal A cancers (p < 10−10) whereas p-mTOR pathway activation was associated with luminal B cancers (p < 10−10)." (PMID 30729154, 2019). "Currently, human cancer genome databases are being mined to aid identification of activated mTOR mutations." (PMID 31075885, 2019). "This article reviews the role of PIK3CA mutations and inhibitors of PI3K/AKT/mTOR pathways in major cancer types and examines its association with clinicopathological parameters and prognosis." (PMID 31905960, 2019). "Various cancer types have been shown to carry druggable targets for mTOR inhibitors, including mutations in MTOR, TSC1, TSC2, NF1, PI3KCA, PIK3CG, STK11, and RHEB." (PMID 31443247, 2019). "The hyperactivation of PI3K/Akt/mTOR signaling was implicated in cancer metastasis and chemoresistance." (PMID 31234823, 2019). "The PI3K/AKT/mTOR signaling pathway has been indicated to be implicated in the development, progression, and metastasis of numerous cancers." (PMID 31756179, 2019). "mTOR signaling pathway is deregulated in most cancers and uncontrolled cell cycle progression is a hallmark of cancer cell." (PMID 31285446, 2019). "Another important aspect of this study was that GRAMD1C expression was correlated with diverse well-known pathways associated with cancer processes and immune responses, such as mTOR signaling pathway, WNT signaling pathway and AKT pathway." (PMID 31875150, 2019). "The PI3K/AKT/mTOR pathway is essential for regulating cell survival and apoptosis and is frequently found mutated and/or overactivated in human cancers." (PMID 31178739, 2019). "A number of cancers overexpress or possess mutated forms of mTOR and of some of the targets of the mTOR kinase signaling." (PMID 30642006, 2019). "Previous studies have implicated downstream mTOR-regulated processes in the hallmarks of cancer: proliferative signaling, metabolic reprogramming, angiogenesis, and metastasis." (PMID 30621584, 2019). "Mutations and genomic alterations in metabolic enzymes and other key regulators of metabolic pathways of which mTOR has been linked are also common in cancers." (PMID 31817676, 2019). "For example, upregulation of PI3K/Akt/mTOR signaling pathway has been implicated in resistance to conventional therapies in many cancer." (PMID 31217782, 2019). "Since the mTOR pathway regulates many basic biological and physiological processes such as cell proliferation, survival and autophagy, it is logical that components in the mTOR pathway are among the most frequently mutated genes in cancers." (PMID 30754640, 2019). "Recent reports have linked BCAT1 expression to mTOR activity in several cancers, although different mechanisms have been proposed [16,18▪▪]." (PMID 29211698, 2018). "Other areas of mTOR signaling covered in these reviews delve into cell migration, inflammation, and regulation of transcription factors linked to cancer progression." (PMID 29848950, 2018). "More recently, an extensive study of more than 11,000 human cancers confirmed the high prevalence of genetic mutations of components of mTOR signalling pathway." (PMID 30061533, 2018). "Mutations in the mTOR gene, that render it constitutively active, have been identified in a few human cancers, even under nutrient starvation conditions, although there are not clearly linked to tumor development." (PMID 29351204, 2018). "In one study, mTOR is found to mediate the effects of circadian disruption caused by hypoxia, which is seen in many disease conditions such as cancer." (PMID 30250482, 2018).